FOXA2 (forkhead box A2)
Diseases named in the same sentence as FOXA2 in open-access papers (continued):
Sharing a sentence is not in itself a finding about the gene and the disease.
colon carcinoma (11 papers, 2010 to 2023). "Taken together, all these data suggested that TRIM36 could directly interact with FOXA2, and induce its K48‐linked polyubiquitination for its protein degradation in colon cancer cells." (PMID 37875418, 2023). "Over-expression of FoxA2 has been linked to colon cancer development and progression." (PMID 24244486, 2013). "Seven out of nine colon tumors exhibited elevated expression of both active β-Catenin and FoxA2 proteins as compared with their paired normal tissues." (PMID 24244486, 2013). "We therefore studied the consequences of functional knockdown of FOXA2 on HNF6 DNA binding activity in the human colon cancer cell line Caco-2." (PMID 20967225, 2010). "FOXA2 was previously implicated in cell proliferation, cancer stem cell maintenance, and an increase in relapse in triple-negative breast cancer, while HNF4A was related to an increase in lymph node and distant metastasis in colon cancer." (PMID 35205397, 2022). "In addition, the expression of forkhead box A2 (FOXA2) in colon cancer tissues is up‐regulated and related to the metabolism and clinical stages." (PMID 33543590, 2021). "We then asked whether FOXA1 and FOXA2 ChIP-seq peak distribution deviated from this pattern at the colon cancer EMT signature genes introduced above." (PMID 29155818, 2017). "Overall, our study aimed for an improved understanding of an inhibitory crosstalk between FOXA2 and HNF6 in metastasizing colon cancer and to utilize this knowledge for the development of an siRNA mediated therapeutic approach." (PMID 20967225, 2010). "Moreover, FOXA2 is capable of facilitating EMT, inhibiting apoptosis and enhancing colon cancer cell invasion ability." (PMID 33543590, 2021).
ovarian carcinoma (10 papers, 2017 to 2024). A malignant neoplasm originating from the surface ovarian epithelium. "FOXA2 was downregulated in the autophagy score-high group of 4 cancer types, and FOXA2 was regulated by autophagy activity in ovarian cancer stem cells." (PMID 36289218, 2022). "proved that autophagy can maintain the dryness of ovarian cancer stem cells through FOXA2, thus promoting the progression of ovarian cancer." (PMID 36353542, 2022). "The enhanced autophagy flux in ovarian cancer stem cells supports self-renewal and chemoresistance through upregulation of the transcription factor Forkhead Box A2 (FOXA2)." (PMID 33743781, 2021). "We have previously reported that miR-590-3p promoted ovarian cancer growth and metastasis, in part by targeting Forkhead box A (FOXA2)." (PMID 31013711, 2019). "Recently, autophagy has been reported to be able to regulate the self-renewal of ovarian cancer stem cells through regulating FOXA2 and favor chemoresistance of ovarian cancer stem cells." (PMID 30319732, 2018). "Autophagy and FOXA2 are therefore potential targets for ovarian cancer stem cell directed therapies." (PMID 29187221, 2017). "High expression of GJB2, S100A2, SPOCK2, TGM1or EPS8 indicated a poor OS of patients with ovarian cancer, whereas ovarian cancer patients with higher expression of ADAMDEC1, CHEK1, EGFL6, FAM181A, FOXA2, LYPD1, PART1 or XPR1 possessed better OS." (PMID 31794425, 2019). "For RFS of patients with ovarian cancer, SPOCK2 and FAXDC2 were unfavorable prognostic biomarkers but ADAMDEC1, CCNA2, FAM181A, FOXA2, LRRTM1, NEIL3 and XPR1 were favorable prognostic biomarkers." (PMID 31794425, 2019). "It was evidenced that inhibition of autophagy in ovarian cancer stem cells decreased the size and number of sphere formation, reduce the population of CD24− and CD44+ cells, increased drug sensitivity to paclitaxel and attenuates the expression of FOXA2." (PMID 33743781, 2021).
endometrial cancer (9 papers, 2015 to 2025). Primary or metastatic malignant neoplasm involving the endometrium (mucous membrane that lines the endometrial cavity). "FOXA2 encodes a transcription factor mutated in 10% of endometrial cancers (ECs), with a higher mutation rate in aggressive variants." (PMID 35703180, 2022). "Other identified transcription factors have also been reported to be associated with tumors, such as FOXA2 in oral cancer and endometrial cancers, HNF1B in prostate cancer." (PMID 36456645, 2022). "Strikingly, the endometrial cancer (EC) genome atlas project in The Cancer Genome Atlas (TCGA) discovered a significant FOXA2 mutation rate among endometrioid adenocarcinomas, the major histologic subtype of EC." (PMID 35703180, 2022). "Sequencing of FOXA2 in 160 primary endometrial carcinomas revealed somatic mutations in 5.7% of serous, 22.7% of clear cell, 9% of endometrioid, and 11.1% of mixed endometrial carcinomas, the majority of which were frameshift mutations." (PMID 31324031, 2019). "FOXA2 has a high mutation rate in aggressive variants of endometrial cancers (ECs)." (PMID 41013561, 2025). "Among 32 TCGA data sets of diverse human cancers (cBioPortal), endometrial carcinomas and carcinosarcomas are the 2 cancer types with the highest incidence of FOXA2 mutation, affirming that FOXA2 plays a particularly important — and perhaps unique — role in endometrial carcinogenesis." (PMID 35703180, 2022). "Research indicates that inactivating both FOXA2 and RTEN leads to lethal endometrial cancers, with FOXA2 suppressing carcinogenesis." (PMID 41013561, 2025). "The observed loss of FOXA2 expression in poorly differentiated endometrial carcinomas and our FOXA2 reexpression studies (which revealed significant roles in cancer cell growth and promotion of cell adhesion to extracellular matrix factors) provoked the question of whether FOXA2 plays a role in EMT." (PMID 35703180, 2022). "MiR-200a facilitates EMT process of endometrial cancer via negatively modulating FOXA2 expression." (PMID 32432654, 2020). "Likewise, FOXA2 and SOX17 are primarily mutated in endometrial cancers, and ELMER identified network alterations specifically in this cancer type (UCEC)." (PMID 25994056, 2015).
melanoma (9 papers, 2016 to 2024). A malignant, usually aggressive tumor composed of atypical, neoplastic melanocytes. "The promoter of miR-765 binds directly to HOXB9, promotes self-transcription and then targets FOXA2 to regulate FOXA2, resulting in a decrease in FOXA2 and an increase in melanoma tumor stem cells." (PMID 33313406, 2020). "Of the cellular populations tested, the eight BCa cell lines expressing FoxA1 or FoxA2 had very high levels of LIPG protein compared with the melanoma MDA435 cell line and the human epithelial cell." (PMID 27045898, 2016). "Furthermore, this study revealed that miR-1246 induces proliferation as well as migration and invasion in melanoma cells by targeting FOXA2." (PMID 39285403, 2024). "Subsequently, FOXA2 impacts different aspects of phenotype malignancy in melanoma." (PMID 37772815, 2023). "In melanoma cells, MiR-1246 inhibited BAX but stimulated Bcl2, thus inhibiting apoptosis and hepatocyte nuclear factor 3-β/FOXA2 which is involved in embryonic development and activates liver genes." (PMID 38899393, 2024). "We compared FoxA1 and FoxA2 mRNA expression in four estrogen receptor positive (ER+) (MCF7, T47D, BT474 and ZR75) and four estrogen receptor negative (ER−) (SKBR3, MDA468, BT20 and MDA231) BCa cell lines, a cell line of melanoma origin (MDA435), and human mammary epithelial cells (HMECs)." (PMID 27045898, 2016).
colorectal cancer (8 papers, 2013 to 2025). A primary or metastatic malignant neoplasm that affects the colon or rectum. "We found that the states of the nodes canalized by the simultaneous perturbation of MYB, HDAC2, and FOXA2 in the Boolean GRN model were similar to the results from the in vitro knockdown experiments on the various colorectal cancer cell lines." (PMID 39661721, 2025). "Together, these results indicate that simultaneous knockdown of MYB, HDAC2, and FOXA2 can induce the reversion of colorectal cancer cells." (PMID 39661721, 2025). "Further down the list, Foxa2 (1.32, rank 10/284) is known to regulate lipid metabolism and ketogenesis related genes in liver, and Lef1 (1.31, rank 11/284) is a prognostic biomarker for liver metastasis in colorectal cancer." (PMID 24238150, 2013). "We measured transcriptome data of three colorectal cancer cells with scramble knockdown (C) and simultaneous knockdown of MYB, HDAC2, and FOXA2 (KD)." (PMID 39661721, 2025). "It has been reported that FOXA2 is highly expressed in colorectal cancer, participates in the epithelial–mesenchymal transition (EMT) process, and is closely related to the metastasis and clinical staging of colorectal cancer." (PMID 34322156, 2021).
endometriosis (8 papers, 2019 to 2025). The growth of functional endometrial tissue in anatomic sites outside the uterine body. "Similarly, FOXA2 deficiency was found to contribute to cell proliferation and migration in eutopic endometrium from patients with endometriosis." (PMID 33411206, 2021). "We also suggest a link between FOXA2 and SRRM2 genes and this endometriosis form, recommending further research on gene mutations and molecular pathways for better diagnosis and understanding." (PMID 41013561, 2025). "Additionally, our study is the first to provide sequencing data, identifying FOXA2 and SRRM2 genes as associated with this form of endometriosis." (PMID 41013561, 2025). "Furthermore, decreased expression of Lif and FOXA2 has been observed in eutopic endometrial cells in patients with endometriosis, along with increased proliferative activity and migratory capacity." (PMID 39195693, 2024). "The WES analysis indicated that FOXA2 and SRRM2 were respectively candidate driver genes for endometriosis in para-aortic lymph nodes and cystic adenomyosis requiring validation in larger cohorts and functional studies." (PMID 41013561, 2025). "It is reported that upregulation of FoxA2 (Forkhead Box A2) downregulates ERβ by transcriptionally inhibiting IGF2BP1, thereby repressing pyroptosis in endometriosis." (PMID 38397379, 2024). "Specifically, the gland-specific transcription factor Forkhead box A2 (FOXA2) is required for LIF expression in mice, but it is decreased in endometrium from women with endometriosis." (PMID 31387263, 2019). "Unlike in endometriosis, FOXA2 expression can be induced by P4 in a healthy endometrium." (PMID 33411206, 2021).
Hepatic steatosis (8 papers, 2012 to 2024). Steatosis is a term used to denote lipid accumulation within hepatocytes. "Recent studies have shown that mutations and abnormal expression of Foxa2 are related to hepatic steatosis." (PMID 38084145, 2023). "The data presented here demonstrated that loss of FOXA2 induced ER stress and increased hepatic steatosis and bile acid toxicity in iPSC-derived hepatocytes." (PMID 35973994, 2022). "Foxa2 ameliorated hepatic steatosis and inhibited the activation of the NF-κB/IKK signaling pathway." (PMID 38084145, 2023). "In conclusion, we demonstrated that Foxa2 ameliorates hepatic steatosis in NAFLD and suppresses NF-κB/IKK signaling pathway activation in OA-stimulated HepG2 cells, thus presenting a new therapeutic target for NAFLD treatment." (PMID 38084145, 2023). "Forkhead box a2 (Foxa2) is proven to be an insulin-sensitive transcriptional regulator and affects hepatic steatosis." (PMID 38084145, 2023). "In this study we showed reduced mRNA expression of ALR, and its transcription factor FOXA2 (HNF3β), in hepatic steatosis and NASH." (PMID 28877220, 2017). "In hyperinsulinemic/obese mice, Foxa2 is permanently inactive, which contributes to the development of hepatic steatosis and insulin resistance." (PMID 22238690, 2012). "p300 can acetylate FOXA2, thereby blocking its nuclear rejection and increasing its transcriptional activity, which further led to increased mitochondrial oxidation, hepatic ketogenesis, insulin sensitivity and attenuated hepatic steatosis in db/db mice." (PMID 36798663, 2023). "Oil Red O staining showed that the accumulation of lipid drops was reduced after oe-Foxa2 treatment, suggesting that Foxa2 could suppress hepatic steatosis in NAFLD mice." (PMID 38084145, 2023). "Therefore, the appropriate expression of FOXA2 in human hepatocytes is essential for normal hepatocyte development and protects hepatic cells from ER stress, hepatic steatosis, and bile acid toxicity." (PMID 35973994, 2022). "Moreover, we show that binding of Foxa2 is increased in a progeroid laminopathy model, similar to increased Foxa2 occupancy in old livers, contributing to etiology of fatty liver and age‐dependent metabolic dysfunction." (PMID 29484800, 2018). "suggest that FOXA2 expression is reduced during hepatic steatosis, and FOXA2 regulates its target endogenous ALR level, which may lead to increased endoplasmic reticulum stress and lipid deposition, reduced fatty acid Β-oxidation, ultimately exacerbating the progression of NASH." (PMID 36798663, 2023). "In addition, a previous study showed that Foxa2 activation ameliorates hepatic steatosis." (PMID 38084145, 2023). "Furthermore, oe-Foxa2-induced FAS and ACC downregulation and CPT1α upregulation was reversed by LPS (NF-κB/IKK pathway activator) treatment, which indicates that Foxa2 attenuates hepatic steatosis may relate to the inhibition of NF-κB/IKK pathway." (PMID 38084145, 2023). "Hepatotoxicity functions in Foxa2 direct targets identified by IPA included highly enriched “liver hyperplasia” (p‐value 1.75 × 10−16) and “liver steatosis” (p‐value 1.80 × 10−6)." (PMID 29484800, 2018). "The effect of FOXA2 on LPL is clear, but further studies are needed to determine whether it can influence fatty acid uptake and liver steatosis through this pathway." (PMID 36798663, 2023). "Therefore it is likely that under the regulation of FOXA2 and Nrf2 diminished endogenous ALR levels in hepatic steatosis result in altered expression of lipid metabolizing genes such as ELOVL6, SCD1, CPT1α as well as FABP1." (PMID 28877220, 2017). "High levels of a constitutively active Foxa2 protein (Foxa2T156A), but not the wild-type protein, can decrease liver steatosis, suggesting that Foxa2 could be a pharmacological target for the treatment of NAFL and for improving liver insulin sensitivity." (PMID 22238690, 2012).
Hypoglycemia (8 papers, 2017 to 2024). A decreased concentration of glucose in the blood. "Most convincingly, heterozygous loss-of-function coding variants in FOXA2 have been reported in at least seven individuals with hypoglycaemia, most of whom also had confirmed HI." (PMID 38605124, 2024). "The six patients reported with FOXA2 mutations come from different races, and their hypoglycemia was picked up in the first year of life." (PMID 37219505, 2023). "In human, previous reports demonstrated that patients with heterozygous FOXA2 mutations develop hyperinsulinemia, hypoglycemia, hypopituitarism, endodermal organ defects, and craniofacial abnormalities." (PMID 33473118, 2021). "We report a case of neonatal hypoglycemia due to hypopituitarism and CH found to have a likely pathogenic change in the FOXA2 that has not been previously reported." (PMID 37219505, 2023). "Similarly, FOXA2 controls insulin secretion; however, FOXA1 and FOXA2 have opposing effects on insulin regulation, and the absence of FOXA2 leads to increased insulin secretion and induces hypoglycemia." (PMID 38605023, 2024). "Furthermore, in mice with endoderm-specific knockout of FOXA2, pancreatic alpha cells did not complete terminal differentiation, resulting in a dramatic reduction in the number of mature alpha cells, triggering hypoglucagonemia and hypoglycemia as well as death." (PMID 38605023, 2024).
cervical cancer (7 papers, 2021 to 2024). A primary or metastatic malignant neoplasm involving the cervix. "Previous studies have shown that miR-141-3p acts as an oncogene in cervical cancer by suppressing its FOXA2 target." (PMID 34180758, 2021). "Another recent study found that miR-141 targets FOXA2 in cervical cancer where FOXA2 silencing mimicked the tumorigenic effect of miR-141 overexpression in cervical cancer cells." (PMID 33682796, 2021). "Approximately one third (7 of 19; SPRR2G, RAET1G, FOXA2, BNIPL, LOR, LCE2B, and LCE1B) had expression that was highest among the NED/Stage1/Stage2 cluster, lower in the premalignant cluster, and even lower in Stage 3 cervical cancer tissue." (PMID 34944802, 2021).
Parkinson disease (7 papers, 2012 to 2025). A progressive degenerative disorder of the central nervous system characterized by loss of dopamine producing neurons in the substantia nigra and the presence of Lewy bodies in the substantia nigra and locus coeruleus. "Nurr1 and Foxa2 exerted a similar protective effect against the parkinsonism toxins MPP+ and 6-hydroxydopamine (6-OHDA) (Fig3B, middle and right)." (PMID 25759364, 2015). "Studies have shown that in a rat model of Parkinson’s disease, co-transplantation of neural stem/progenitor cells (NSCs/NPCs) with midbrain-derived astrocytes overexpressing the transcription factors NURR1 and FOXA2 promotes graft maturation and survival, thereby improving treatment outcomes." (PMID 39026989, 2024). "A series of genes, including mCherry and various combinations of the neural transcription factors LMX1a, FOXA2 and OTX2, were inserted in recipient cell lines derived from H9 ESC, as well as iPSC lines derived from a Parkinson’s disease patient and a normal sibling control." (PMID 24304893, 2014).
steatosis (7 papers, 2012 to 2023). Increased lipid within the cytoplasm of cells. "However, other studies have shown that high levels of Foxa2 in transgenic mice cause postnatal steatosis, which likely results from de novo lipid synthesis." (PMID 22238690, 2012). "In addition, 3 genes related to fatty acid oxidation were regulated with insulin receptor substrate 2 (IRS2) being up-regulated whereas carnitine palmitoyltransferase 1 (CPT1) and forkhead box protein A2 (FOXA2) being down-regulated, all of which are mechanistically linked to steatosis." (PMID 25470483, 2014). "We have previously shown that ALR expression is regulated by FOXA2 (HNF3β) and therefore we analyzed FOXA2 mRNA expression in human liver samples with steatosis or NASH." (PMID 28877220, 2017). "We found a significant reduction of FOXA2 in steatosis (1.98 ± 0.19) and NASH (1.56 ± 0.19) compared to normal liver (2.52 ± 0.22), which in part correlates with ALR expression in the same tissue samples." (PMID 28877220, 2017). "Analyzing a cohort of human liver samples we found reduced ALR and FOXA2 expression in steatosis and NASH patients." (PMID 28877220, 2017). "Previous findings demonstrated that elevated levels of Foxa2 activate the expression of lipogenic genes (inducing steatosis) and MTP (increasing VLDL secretion)." (PMID 22238690, 2012). "Increased occupancy of FOXA2 in the aging liver can de-repress PPAR and LXR-dependent gene expression, leading to the development of steatosis." (PMID 36798663, 2023). "In contrast, hepatic PPARα, PPARβ/δ, Foxa2, and circadian clock BMAL1 exert anti-steatosis action by promoting fatty acid β oxidation." (PMID 30013137, 2018). "We also found that Foxa2 occupies considerably more regions in aged fatty liver, binding regions of decreased nucleosome occupancy at PPAR targets, and cooperating with PPAR receptors in regulation of gene expression changes that contribute to steatosis." (PMID 29484800, 2018). "Winged‐helix transcription factor Foxa2 plays an important role in lipid homeostasis in aged liver, binding regions of decreased nucleosome occupancy near PPAR‐dependent lipid synthesis and storage genes and contributing to gene expression changes that lead to steatosis." (PMID 29484800, 2018).